GPR55 (G protein-coupled receptor 55)
Diseases named in the same sentence as GPR55 in open-access papers (continued):
Sharing a sentence is not in itself a finding about the gene and the disease.
cancer (continued). "Moreover other cannabidiol‐related studies reported inhibition of GPR55 expression, which is related directly or indirectly to cell changes promoting malignant growth, including uncontrolled cancer cell proliferation, angiogenesis, cancer cell adhesion, cancer cell migration, and metastasis." (PMID 39503169, 2024). "Remarkably, GPR55-dependent BMMC chemotaxis was observed towards conditioned media from distinct mouse and human cancer cells." (PMID 37047288, 2023). "Taken together, GPR35 and GPR55 influence the IBD and cancer features such as regulation of inflammation, pain, metabolic changes, and hypoxia." (PMID 37834122, 2023). "Specifically, GPR55 dimer formation with cannabinoid receptors has been previously observed in neutrophils, transfected HEK293 cells, and cancer cells." (PMID 37047288, 2023). "LPI was reported as the endogenous agonist of GPR55, being expressed in various cancers in an aggressiveness-related manner, suggesting a role of the LPI/GPR55 axis in cancer." (PMID 35562947, 2022). "G-protein-coupled receptor GPR55 (CB3), also called orphan receptor, reportedly promotes cancer cell proliferation, both in cell cultures and in xenografted mice, and has thus become an important new biomarker and therapeutic target." (PMID 36497400, 2022). "Depending on the heteromer formation, different eCBome signalling changes related to cancer can be observed, including an enhancement of CB1 signalling with GPR55, inhibition of GPR55 signalling, and modulation of CB2 activation." (PMID 35204820, 2022). "Cannabinoid signaling in the context of cancer progression and development has been primarily investigated through three receptors, CB1, CB2, and GPR55, and each displays its own unique effects in various contexts." (PMID 34313032, 2022). "GPR55 is a GPCR of the non-CB1/CB2 cannabinoid receptor family, which is activated by lysophosphatidylinositol (LPI) and stimulates the proliferation of cancer cells." (PMID 33435517, 2021). "Although in a non-cancer model, it has been reported that UVA-UVB exposition of human skin fibroblast increased CB1R/2 and GPR55 expression, resulting in a pro-inflammatory and pro-oxidant response." (PMID 34943903, 2021). "Due to the apparent importance of their receptors in certain cancer types, two atypical cannabinoids, abnormal CBD (Abn-CBD) and O-1602 that mediate their effects through GPR55 and GPR18, were selected in our study." (PMID 31611800, 2019). "This is based on the finding that the cannabinoid CB2 receptor and the GPCR55 (GPR55) are overexpressed in cancer cells and human tumors and that they form heterodimers displaying antagonistic CB2-GPR55 interactions in cancer cells." (PMID 30833931, 2019). "We therefore examined the mRNA expression of seven cannabimimetic receptors – CNR1 (CB1), CNR2 (CB2), GPR55, TRPV1, TRPV2, TRPA1, TRPM8 – and found them to be differentially expressed amongst the 12 tested cancer cell lines." (PMID 31289609, 2019). "GPR55 is an untypical cannabinoid receptor, which elicits Rho, Rac and CD42 signaling, converging on the regulation of cancer and endothelial cell migration and tube formation." (PMID 26875980, 2016). "Several studies highlighted the role of GPR55 in several types of cancer and we have recently reviewed the role of the LPI/GPR55 axis in cancer." (PMID 26784247, 2016). "The GPR55 endogenous ligand, LPI is secreted by fibroblasts and epithelial cancer cells and transformed thyroid cells, leading to mitogenic effects." (PMID 25926795, 2015). "However, they can also activate transient receptor potential vanilloid 1 (TRPV1) and inhibit G protein-coupled receptor 55 (GPR55), inducing endoplasmic reticulum stress, leading to cancer cell death independently of canonical cannabinoid receptors." (PMID 41011117, 2025). "Furthermore, it has been demonstrated that GPR55 stimulates the extracellular signal-regulated kinase (ERK) cascade, which in turn stimulates the growth of cancer cells." (PMID 38895631, 2024).
cancer (continued). "By using GPR55 KO mice in this model, we created a situation where GPR55 was present in cancer cells, but not in cells of the TME." (PMID 39885986, 2024). "Although involvement of the LysoPI/GPR55 axis in the pathogenesis of cancer has been proposed, it has still not been established." (PMID 35315587, 2022). "Concordant with the results of the mitochondrial membrane potential in vitro, these two protein expression levels were enhanced in the cancer tissues of the mice injected with SPL overexpressing cells, but declined in those of the mice injected with SPL or GPR55 deleted cells." (PMID 36125914, 2022). "GPR55 transcript (mRNA) levels in EC tissues were three times as high as in the control (atrophic endometria obtained from post-menopausal women without cancer; n = 6) (p = 0.002)." (PMID 34324032, 2021). "In contrast, blockade of G12/13 signaling by means of a GFP-RGS chimera did not alter LPI-induced GPR55-mediated cancer cell invasion." (PMID 27340777, 2016). "This suggests that cancer cells may release LPI and promote proliferation in an autocrine loop via GPR55." (PMID 25926795, 2015). "Lack of GPR55 in the TME of KPCY55 tumors from KO mice caused a shift in the immune cell profile towards increased numbers of CD8+ T and NK cells, which are known for their cytotoxicity against cancer cells." (PMID 39885986, 2024). "GPR55 is a non-canonical cannabinoid receptor, important for cancer proliferation." (PMID 36982628, 2023). "Similarly, while both Δ9-THC and CP-55,940 act as full agonists at both GPR18 and GPR55, both of these cannabinoid ligands are unable to bind non-canonical CBRs expressed in all the cancer cells investigated." (PMID 35328467, 2022). "In addition to GPR55 inactivation, CBD may effectuate additional anti-cancer effects through other targets in the eCBome, including negative allosteric modulation of CB1 receptors and partial agonism of CB2 receptors." (PMID 35204820, 2022). "Interestingly, compared with studies examining CB1‐ and CB2‐induced migration of cancer cells, the variability of responses, with activation inducing both pro‐ and anti‐migratory effects has not been convincingly demonstrated in GPR55 studies." (PMID 34313032, 2022). "We hypothesized that other endocannabinoids and structurally similar compounds, which are not substrates for the FAAH, could also induce cancer cell death via GPR55 activation and have no stimulatory effect on cancer cells." (PMID 33435517, 2021). "Downregulation of GPR55 inhibited cancer cell proliferation without addition of exogenous LPI." (PMID 25926795, 2015). "Cannabinoids may reduce colonic polyp formation, intestinal inflammation, and reduce cancer cells growth via cannabinoid 1 (CB1), cannabinoid 2 (CB2) receptors, transient receptor potential cation channel subfamily V member 1 (TRPV1) receptors, and G-coupled protein receptor 55 (GPR55)." (PMID 34503163, 2021). "On the contrary, peptide agonist PACAP27/38 is downregulated in cancer, which may be indicative for lack of its specificity as GPR55 ligand (PACAP27/38 activates also PAC1 receptor) or signaling bias at GPR55." (PMID 34948125, 2021). "In cancer murine 4T1 and human MCF-7 mammary carcinoma cells, the action of JWH-015 seems to be complex, since it is not mediated either by CB1R or CB2R, or by GPR55, TRPV1, or TRPA1 receptors." (PMID 31214034, 2019).
tumor (59 papers, 2013 to 2026). "In our experiments, we also saw less Ki-67 expression in tumor cells of GPR55 KO mice, suggesting reduced proliferation through deficiency of GPR55." (PMID 39885986, 2024). "Recently, the GPR55 was demonstrated as having an association with tumor cell proliferation of different tumor cell lines." (PMID 33802282, 2021). "In the azoxymethane/dextrate sulfate sodium (AOM/DSS) animal model of CAC, activation of GPR55 caused changes in myeloid-derived suppressor cells and T lymphocytes that are usually present within the tumor’s microenvironment." (PMID 34503163, 2021). "Although the intracellular effect of LPI and its receptor GPR55 has been extensively studied, to this date a causative role of LPI/GPR55 in (tumour) angiogenesis in vivo and its underlying molecular mechanism in endothelial cells remains uncharacterized." (PMID 25989290, 2015). "Hence, we underlined a novel role for lactate as an activator of GPR55 in PCa cells, supporting amoeboid-like tumor cell migration." (PMID 40434517, 2025). "Similarly, in advanced stages of pancreatic ductal adenocarcinoma, elevated GPR55 expression is linked to increased tumor aggressiveness." (PMID 40565152, 2025). "Deficiency of GPR55 in the TME led to reduced tumor weight and volume, and altered the immune cell composition of tumors, favoring an anti-tumorigenic environment by increasing the number of CD3+ T cells, particularly CD8+ T cells, and the expression of PDL1 on macrophages." (PMID 39885986, 2024). "Since GBMs are characterized by a very high number of genetic alterations causing changes in proliferation, migration, and invasiveness of tumor cells, it is very likely that one downstream effector molecule of GPR55 might be mutated in GBM #23, resulting in a disruption or a shift of its signaling." (PMID 33802282, 2021). "Lyso‐phosphatidylinositol (LPI) is generated by PLA2 and a G protein receptor 55 (GPR55), upregulated in human cSCC and suggested to promote skin carcinogenesis and tumor aggressiveness." (PMID 38721854, 2024). "GPR55 mRNA expression (which should only derive from GPR55-expressing tumor cells) was significantly lower in tumor samples of GPR55 KO vs. WT mice." (PMID 39885986, 2024). "Although macrophages, neutrophils, mast cells, and tumor cells treated with a GPR55 antagonist decrease their migratory behavior, we observed increased migration of pan-T cells, isolated from healthy GPR55 KO mice." (PMID 39885986, 2024). "In a word, our analysis demonstrated that GPR55 is a good indicator for assessing the tumor immune microenvironment and predicting the immunotherapy responses of HCC." (PMID 37688769, 2023). "GPR55 is a lipid-sensing receptor that plays important roles in cell mobilization, invasion and cell cycle progression in tumor development." (PMID 37642951, 2023). "Conversely, GPR55 was positively correlated with these biomarker mRNAs in lymph nodes of stage I patients known to generally lack tumor cells." (PMID 35562947, 2022). "For LysoPI and LysoPG, the expression of GPR55 increased and the levels of LysoPG increased within the Colon‐26 tumor xenograft tissue." (PMID 35315587, 2022). "Significant attenuation of tumor-induced osteoclastogenesis was induced by one of the GPR55 antagonists, CBD." (PMID 36614130, 2022). "Contrary to this, the activation of GPR55, has been shown to promote tumor growth in various types of cancer and alters the populations of myeloid-derived suppressor cells and T lymphocytes within the tumor tissues." (PMID 35634468, 2022). "In summary, these results show that (R,S′)-MNF is a potent inhibitor of tumor growth, eliciting its antitumorigenic effect through GPR55 and metabolic deprogramming." (PMID 35256673, 2022). "If GPR55 has a physiological effect, it is probably through its role in innate immunity and tumor immunosurveillance." (PMID 35562947, 2022).
tumor (continued). "GPR55 acts as regulator in innate immunity and tumor immunosurveillance via stimulatory effects in immune cells, such as T cells and NK cells." (PMID 35562947, 2022). "GPR55 is highly expressed in T cells and B cells, cell types that dominate in a healthy lymph node, whereas lymph nodes heavily infested with tumor cells contain relatively fewer lymphocytes." (PMID 35562947, 2022). "The present results are consistent with previous reports that suggest that GPR55 knockout mice have less tumour-induced mechanical hypersensitivity than control littermates, and failed to develop mechanical hyperalgesia in the partial nerve ligation model." (PMID 35056124, 2022). "In breast cancer, GPR55 has been found to heterodimerize with CB receptors and its targeting reduces tumor growth." (PMID 34064197, 2021). "Sub-analysis indicated that GPR55 levels in the estrogen-dependent Type 1 EC tumours (n = 15) were responsible for this increased expression." (PMID 34324032, 2021). "Since GPR55 promotes proliferation, migration, invasion, and metastasis of different tumor cells, its expression has been correlated with tumor aggressiveness; higher histological grades; and, in the case of gliomas, lower survival rates." (PMID 33802282, 2021). "GPR55 is up-regulated in CRC tumor tissue, and such alteration was reported to lead to changes in immune cells." (PMID 33692961, 2021). "More and more studies have been conducted to address the relevance of GPR55 in the context of human tumor diseases." (PMID 33802282, 2021). "The highest expression of GPR55 protein was observed in samples from the Type 2 EC group, which is considered a highly aggressive tumour." (PMID 34324032, 2021). "Immunohistochemistry analysis of the tumours revealed CBD inhibition of GPR55 affected signalling pathways involved in gemcitabine resistance." (PMID 34259916, 2021). "LPI activity is correlated with tumor growth and aggressiveness via its interaction with G protein-coupled receptor 55 (GPR-55)." (PMID 32571262, 2020). "These heterodimers of CB2-R and GPR55 influence tumor growth by modulating cyclic adenosine monophosphate (cAMP) signaling and the ERK-1/2 pathways." (PMID 30987191, 2019). "THC was shown to antagonize the tumor-promoting GPR55, both at the single receptor level and within the CB2-R-GPR55 heterodimers." (PMID 30987191, 2019). "Altogether these findings suggest that GPR55 represents an intriguing target for the design of chemotherapeutic agents that can interfere with tumor growth." (PMID 28029647, 2017). "GPR55 expression was examined in human tumor biopsy samples from breast, pancreatic, and glioblastoma patients." (PMID 29066974, 2017). "GPR55 expression levels correlate with tumor aggressiveness, and they are significantly elevated in high-grade tumors." (PMID 28029647, 2017). "GPR55 is also activated by 2-AG-ether, a precursor of 2-AG, which is also known as noladin ether and is likely directly produced and released by the tumor." (PMID 26875980, 2016). "Women with high tumor GPR55 mRNA expression presented reduced overall survival than those with low GPR55 mRNA levels." (PMID 27340777, 2016). "We have provided the following lines of evidence that miR-675-5p inhibits tumor growth, proliferation and migration in part by suppressing GPR55." (PMID 25889562, 2015). "In summary, our results show that LPI is a (ovarian) tumour-derived pro-angiogenic factor that acts through GPR55-dependent activation of ERK1/2 and p38 in endothelial cells." (PMID 25989290, 2015). "Likewise, in colorectal cancer, high tumor-specific GPR55 mRNA expression significantly correlates with decreased relapse-free survival." (PMID 40565152, 2025). "To elucidate whether PD-1 inhibition was more effective in GPR55 KO than WT mice, we evaluated the % differences (Δ) in tumor weights/volumes between isotype control and anti-PD-1 antibody treatment in both groups." (PMID 39885986, 2024).
tumor (continued). "We can demonstrate that deficiency of GPR55 in the TME of murine PDAC tumors leads to improved immune cell infiltration and upregulation of genes involved in T cell activity and function, indicating that TME-derived GPR55 may promote a “cold” tumor." (PMID 39885986, 2024). "Our study indicates that GPR55 in TME cells may drive tumor growth by suppressing T cell functions, such as migration, in a model of PDAC, making it an interesting target for immunotherapies." (PMID 39885986, 2024). "However, our ISH findings indicated that KPCY tumor cells, although hardly expressing GPR55 mRNA in culture, upregulated GPR55 mRNA in situ." (PMID 39885986, 2024). "A pronounced immune response could also be the reason why KPCY55-induced tumors grew slower (appropriate tumor size for harvesting after 29 days) than KPCY-induced tumors in GPR55 KO mice (harvested after 21 days)." (PMID 39885986, 2024). "The treatment did not further decrease tumor growth in GPR55 KO mice, most likely because it had already been robustly reduced by GPR55 deficiency alone." (PMID 39885986, 2024). "We can only speculate that overexpression of GPR55 in tumor cells may have taken part in the tumor progression of WT mice after PD-1 blockade." (PMID 39885986, 2024). "Recent data have demonstrated that GPR55 is expressed by different human tumor entities, and its activation by its ligand L-α-lysophosphatidylinositol (LPI) has tumor-promoting effects reflected by an increased tumor cell proliferation, migration, and invasion capacity." (PMID 37998380, 2023). "Moreover, tumor tissues from GPR55 KO mice show reduced expression levels of tumorigenic factors COX-2 and STAT3." (PMID 35634468, 2022). "Thus, more tumor cells in the node means fewer lymphocytes and therefore lower GPR55 levels and vice versa." (PMID 35562947, 2022). "Both (R,S′)-MNF and (R,R′)-MNF effectively inhibit GPR55 activation, which may be the source of some of their effects on tumor growth and viability." (PMID 35256673, 2022). "The finding that GPR55 is essentially a lymphocyte marker in lymph nodes can be used to complement biomarkers that identify CC tumor cells either by performing combined marker analysis or by calculating a marker ratio and using this ratio to allocate the patients into a positive or negative group." (PMID 35562947, 2022). "In our study, GPR55 was detectable in patient-derived tumor cells of human GBMs." (PMID 33802282, 2021). "In this study, we mapped out the expression pattern for GPR55 in both Type 1 and Type 2 EC and demonstrated that it was higher in the EC than in control samples and this increased expression was related to tumour type and grade, both at the transcript (p = 0.002) and protein (p < 0.0001) level." (PMID 34324032, 2021). "Results showed that um-PEA inhibited tumor cell proliferation via peroxisome proliferator-activated receptor α and G protein-coupled receptor 55, induced cell cycle arrest in the G2/M phase, possibly through cyclin B1/CDK1 upregulation, and induced DNA fragmentation." (PMID 33923494, 2021). "Previous studies have demonstrated that GPR55 protein is present in the normal brain, gastrointestinal tract, spleen and adrenals and its expression is increased in a number of tumours." (PMID 34324032, 2021). "In addition, the ability of GPR55 to promote tumor cell proliferation was also reported in vivo, where a receptor knockdown diminished tumor growth in a xenograft-based model of GBM." (PMID 33802282, 2021). "The distinct genetic background due to the inter- and intratumoral heterogeneity might be responsible for a tumor- and cell-type specific response after activation of GPR55." (PMID 33802282, 2021). "They analyzed the publicly available The Cancer Genome Atlas (TCGA) microarray data sets and found that women with basal/TNBC and high tumor GPR55 mRNA expression had reduced overall survival and reduced metastasis-free survival in comparisson to those with low GPR55 mRNA levels." (PMID 32106399, 2020).